IGHV3OR15-7 (immunoglobulin heavy variable 3/OR15-7 (pseudogene))
Synonyms: IGHV3/OR15-7
Gene: Immunoglobulin variable (V) gene on chromosome 15 (19,987,656 to 19,988,117, reverse strand). Ensembl gene ENSG00000259490.
Gene Ontology:
Molecular function: antigen binding
Biological process: immunoglobulin mediated immune response
Cellular component: extracellular region; plasma membrane
Homologues: Orthologues: mouse Ighv7-3 (72% identical), mouse Ighv7-1 (69% identical), mouse Ighv7-4 (69% identical), mouse Ighv7-2 (65% identical). Paralogues in human: IGHV3-72 (89% identical), IGHV3-73 (85% identical), IGHV3-49 (82% identical), IGHV3-15 (80% identical), IGHV3-66 (77% identical), IGHV3-23 (76% identical), IGHV3-64 (76% identical), IGHV3-74 (76% identical), IGHV3-11 (76% identical), IGHV3-53 (76% identical), IGHV3-43 (75% identical), IGHV3-64D (75% identical), and 65 more.